RIPK1 (receptor interacting serine/threonine kinase 1)
Diseases named in the same sentence as RIPK1 in open-access papers (continued):
Sharing a sentence is not in itself a finding about the gene and the disease.
tumor (continued). "Therefore, it is possible that another tumor suppressor function for CYLD may be to activate the RIPK1 death-signaling response, and antagonizing this death pathway by deleting or otherwise inhibiting CYLD would be expected to provide a survival advantage to tumors." (PMID 32024820, 2020). "To further verify that necroptosis was involved in this cell death, we detected RIPK1 and RIPK3 expression levels in NGP xenograft tumor tissues by immunohistochemistry staining." (PMID 32116708, 2020). "We measured relative mRNA expression levels of RIPK1, RIPK3, and MLKL in tumor and corresponding normal lung tissues." (PMID 32742497, 2020). "We now report that phosphorylation of CYLD by IKK family kinases in HTLV-1 transformed T cells inhibits RIPK1 from activating the cell death pathway and inhibiting these kinases reactivates CYLD and RIPK1-dependent tumor cell death." (PMID 32024820, 2020). "We further evaluated the protein expressions of autophagy markers (ATG5, ATG7, Beclin-1, and LC3 B) and necroptosis markers (RIPK1, RIPK3) in NGP xenograft tumor tissues after rapamycin and MK-2206 combination treatment by Western Blot." (PMID 32116708, 2020). "In this sense, we evaluated the prognostic value of the ZNF611, ZNF304, RIPK1, TNFRSF21, DUSP8 and HRAS genes according to tumor subtypes." (PMID 30938061, 2019). "While we have observed small differences in terms of absolute uptake in tumor and normal organs between the L19-TNF alone or in combination with the RIPK1 inhibitor GSK’963, the tumor-selectivity for the immunocytokine was preserved." (PMID 31803362, 2019). "Although this study demonstrated the promoting effect of RIPK1 and RIPK3 in tumor development, necroptosis of tumor cells during tumor progression was not investigated." (PMID 31922095, 2019). "It is therefore interesting to note that Gemcitabine, has been shown to increase RIPK1 and RIPK3 expression, thereby, potentially promoting tumour progression in PDAC patients, albeit unintentionally." (PMID 31416294, 2019). "In summary, our study shows the kinase activity of RIPK1 and RIPK3 has a physiological role in the tumor microenvironment, in particular tumor cell extravasation and remodeling by altering the downstream signaling pathways of permeability factors." (PMID 28151480, 2017). "Here we show that, contrary to expectation, necroptotic factors RIPK1, RIPK3, and MLKL promote tumor growth." (PMID 26959742, 2016). "In our study, we evaluated the effects of the necroptotic genes RIPK1, RIPK3, and MLKL in tumor growth and tumor resistance to therapy." (PMID 26959742, 2016). "In non-tumor diseases, studies have shown that TNF-induced palmitoylation of RIPK1 (mediated by DHHC5 and dependent on its K63 ubiquitination) is a key mechanism that activates RIPK1 kinase activity and bypasses the cell death checkpoint, thereby inducing downstream apoptosis/necroptosis." (PMID 40977744, 2025). "This suggests that the combination treatment may have enhanced the TNFR1 signaling axis to activate the RIPK1/RIPK3 pathway, further driving necroptosis and promoting inflammatory responses within the tumor immune microenvironment." (PMID 41008944, 2025). "RIPK1 was phosphorylated at site S25 in resistant but not sensitized tumor cells in response to T cell challenge." (PMID 41315176, 2025). "Notably, RIPK1 and RIPK3 were highly expressed in normal tissues, suggesting their potential roles as tumor suppressors in KIRC progression." (PMID 40969770, 2025). "Further assessment demonstrated that the expression of necroptosis-related genes, including FADD, MLKL, TLR2, PGAM, HMGB1, CXCL 1, TRAF2, and EZH2, was elevated in tumor tissue, while FAS, RIPK1, RIPK3, TLR3, TNFRSF, ALDH2, and NDRG2 were upregulated in normal intestinal tissues." (PMID 40959081, 2025). "Moreover, by degrading RIPK1, LD4172 promotes TNF-α-induced apoptosis and immunogenic cell death, thereby remodeling the tumor immune microenvironment." (PMID 40301325, 2025).
tumor (continued). "In contrast, RIPK1 degraders employ the ubiquitin-proteasome system to completely clear RIPK1, simultaneously ablating scaffold-mediated survival signals and relieving inhibition on the RIPK3-MLKL pathway, significantly enhancing anti-tumour immunity." (PMID 41334873, 2025). "The expression and functional status of key molecules within the PANoptosome, such as ZBP1, RIPK1, RIPK3, CASP8, and ASC, may influence tumor viability and immune detection." (PMID 40422233, 2025). "Investigating tumor therapy strategy in tumors with high expression of SPOP and RIPK1." (PMID 41122967, 2025). "Our findings suggest that targeting proteins involved in RIPK1 pro-survival checkpoints and promoting direct RIPK1 activation is a viable mechanism to potentiate TNF-induced cell death and enhance the impact of immune cell-mediated tumor clearance." (PMID 41315176, 2025). "It is not difficult to see that targeting RIPK1/RIPK3 in macrophages has the potential to be a potent target to restrain tumour progression." (PMID 38652105, 2024). "Another study demonstrated reduced or absent expression of RIPK3 in human AML primary samples without variations in RIPK1, highlighting the potential of tumor cells to escape necroptosis to survive." (PMID 38730609, 2024). "It has also been found that activation by TNF-α and RIPK1 is not always required for necroptosis of tumor cells in different cancer models." (PMID 39062119, 2024). "To test whether inhibition of RIPK1 kinase activity also enhances tumor responses to ICB therapy, we treated B16F10 xenograft tumors with the RIPK1 kinase inhibitor T2I, alone or in combination with anti-PD1." (PMID 39681571, 2024). "In addition, RIPK1 and RIPK3 are strongly correlated with high levels of tumour migration and metastasis in pancreatic cancer." (PMID 38652105, 2024). "Mice treated with either endothelial cell-specific RIPK3 deletion or receptor-interacting serine/threonine-protein kinase 1 (RIPK1)-inhibitor necrostatin-1 showed a reduction in tumor-cell-induced endothelial necroptosis, tumor cell extravasation, and metastasis." (PMID 39090094, 2024). "Notably, RIPK3-dependent necroptosis activation downstream of RIPK1 contributes significantly to antileukemic activity, supporting the identification of RIPK3 as a tumor suppressor." (PMID 38730609, 2024). "RIPK1 and RIPK3 are mainly involved in controlling and executing necroptosis in keratinocytes, while RIPK4 controls proliferation and differentiation of keratinocytes and thereby can act as a tumor suppressor in skin." (PMID 37688617, 2023). "In addition, fragile X mental retardation protein (FMRP) binds to RIPK1 mRNA, and treatment with FMR1 anti-transcription upregulates RIPK1, leading to the necroptosis of CRC cells and the inhibition of tumor growth." (PMID 37238692, 2023). "While Utilizing Nec-1 to treat mice or specific knockout RIPK1/MLKL could inhibit the necroptosis in endothelial cells, further decreasing tumor extravasation." (PMID 37169000, 2023). "Another study confirmed that RIPK1 and RIPK3 may be highly expressed in tumor-reactive T cells and undergo necrosis upon restimulation of the T cell receptor (TCR) with cognate antigen, which can be inhibited via RIPK1 inhibition." (PMID 37061535, 2023). "Therefore, we will further zoom in on the function of RIPK1 and -3 in keratinocyte cell death and the role of RIPK4 in epidermal differentiation and tumor suppression." (PMID 37688617, 2023). "Similarly, inhibition of receptor-interacting serine threonine kinase 1 (RIPK1) enhanced STAT1 signalling and the activation of cytotoxic T cells contributing to anti-tumour activity." (PMID 37752135, 2023). "RIPK1 and RIPK3 control and execute necroptosis in keratinocytes, as in other cell types, while RIPK4 controls proliferation and differentiation of keratinocytes and thereby can act as a tumor suppressor in skin." (PMID 37688617, 2023).
tumor (continued). "However, the inhibitors of apoptosis (IAP) are frequently overexpressed in tumour cells, protecting them from TNF-induced, RIPK1-mediated cell death." (PMID 35327375, 2022). "Moreover, DMW also activated RIPK1, RIPK3, and MLKL axis in tumour tissues from xenograft mice, thus, suggesting a necroptotic effect." (PMID 35955595, 2022). "Although GSK′547 was an excellent tool for exploring RIPK1 inhibition in mouse tumor models, its high turnover rate in human hepatocytes did not possess the necessary characteristics as a clinical lead compound." (PMID 36249746, 2022). "Interaction network results revealed that BAK1, NLRP1, CHMP7, and RIPK1 genes could interact with immune factors, including TNF-α, suggesting their influence on the immune microenvironment of the HNSCC tumor." (PMID 36246601, 2022). "While both RIPK1 and ZBP1 are capable of recruiting RIPK3 to mediate necroptosis, our results indicate that there is little redundancy among these two proteins in mediating tumor necroptosis during tumor development." (PMID 33976222, 2021). "Previous reports studied the possible involvement of necroptosis in tumor development and metastasis, using RIPK1 or RIPK3 KO cells/mice without directly examining tumor necroptosis." (PMID 33976222, 2021). "Since RIPK1 is not essential for necroptosis of tumor cells during tumor development, we searched for possible tumor necroptosis mediators upstream of RIPK3." (PMID 33976222, 2021). "In this current study, we report that Z-DNA-binding protein 1 (ZBP1), not RIPK1, mediates necroptosis of tumor cells during tumor development in preclinical cancer models." (PMID 33976222, 2021). "Consistent with our early finding that RIPK1 is not required for tumor necroptosis during tumor development, we found that RIPK1 is not required for GD-induced MLKL phosphorylation." (PMID 33976222, 2021). "Here, we report that Z-DNA-binding protein 1 (ZBP1), not RIPK1, mediates tumor necroptosis during tumor development in preclinical cancer models." (PMID 33976222, 2021). "Importantly, we found that RIPK1 deletion actually increased, instead of reducing, tumor necrosis and MLKL phosphorylation in RIPK1 KO tumors." (PMID 33976222, 2021). "The relative immunointensity of RIPK1 was low in CCA tissues but negative in adjacent tumor tissues." (PMID 33036630, 2020). "Notably, RIPK1, RIPK3 and/or MLKL are downregulated in various types of cancer, reflecting the necessity for tumor cells to circumvent necroptosis." (PMID 32366830, 2020). "Even though SM are well tolerated, they have limited single agent efficacy in most cancers due to the low concentration of TNF in the tumour microenvironment that would drive RIPK1‐dependent cell death in the absence of cIAPs." (PMID 32419365, 2020). "Studies by Yatim and colleagues and Aaes and colleagues showed that RIPK1 and NF-kB signaling can mediate cross-priming of CD8+ T cells and that vaccination with necroptotic cells induces efficient anti-tumor immunity, respectively (the latter the gold standard for immunogenic death)." (PMID 33003477, 2020). "Two weeks after intravenous injection of RFP-LL/2 cells, RFP+ LL/2 cells were isolated from the tumor tissues by flow cytometer sorting and no signal of phosphorylated RIPK1 was detected in these tumors cells." (PMID 31235688, 2019). "However, somewhat counterintuitively, the expression of RIPK1 and RIPK3 was tumour promoting in this case." (PMID 31416294, 2019). "Inhibition of RIPK1 did not interfere with selective accumulation of L19-TNF into neoplastic lesions, where high local concentrations of TNF caused onset of tumor vascular shutdown and selective hemorrhagic necrosis." (PMID 31803362, 2019). "However, the idea that proteins of the core pathway of necroptotic cell death (RIPK1/3 and MLKL) can promote tumour growth has been recently published." (PMID 29434255, 2018).
tumor (continued). "To validate whether necroptosis and/or apoptosis are involved in the tumor killing mediated by PTT of GNRs-FA, we treated B16-BL6 using GNRs-FA or PBS, in the presence of RIPK1 inhibitor Nec-1 that blocks necroptosis pathways." (PMID 29880902, 2018). "A previous study also showed that RIPK1 is cleaved at normal pH but not cleaved at acidic pH in tumor cells." (PMID 28884134, 2017). "Taken together, we conclude that pro-necroptic factors such as RIPK1, RIPK3, and MLKL may play a role in supporting tumor growth, and MLKL may be a promising target for cancer treatment." (PMID 26959742, 2016). "Clearly, the drug-sensitizing effect of RFC11 in cancer cells is noticeable which is reflected in its synergistic anticancer effect and for its very prominent simultaneous upregulation of RIPK1 and RIPK3 expressions, as are evident in cellular and tumor levels." (PMID 27556106, 2016). "Our novel data suggested that FTY720, but not P-FTY720, directly binds and targets I2PP2A/SET, mimicking ceramide/sphingosine, which activates tumour suppressor PP2A, subsequently suppressing lung tumour growth selectively via inducing RIPK1-mediated necroptosis." (PMID 23180565, 2013). "In addition, the higher expression of RIPK1, RIPK3, and MLKL implicates tumor necroptosis." (PMID 40739587, 2025). "Furthermore, RIPK1/3 was shown to be independent of necroptosis to mediate anti‐tumour effects and inflammatory effects in TME." (PMID 38652105, 2024). "However, according to proteinatlas.org, VHL expression is ubiquitous in major organs, which does not explain the tumor-selective RIPK1 degradation induced by LD4172." (PMID 39681571, 2024). "However, there was no detectable expression of RIPK1 or phosphor-MLKL in our xenografted tumours that had been treated with placental EVs." (PMID 37503762, 2023). "In addition, high NRGscore patients always had more mRNA levels of three necroptosis-driving genes (MLKL, RIPK1, and RIPK3), further validating that necroptosis could play a tumor-promoting role in HCC." (PMID 35875102, 2022). "However, RIPK1 and RIPK3, the major components of necrosomes in PC, were upregulated, and cell immunity was induced by C-X-C motif chemokine ligand 1 (CXCL1) and Mincle to promote tumor growth." (PMID 35740953, 2022). "While this decrease of RIPK1 level in tumor cells may accelerate ZBP1-induced tumor necroptosis, loss of RIPK1 combined with the increase of ZBP1 expression is not sufficient to trigger necroptosis in tumor cells as observed in RIPK1 KO MVT-1 tumors." (PMID 33976222, 2021). "Although it has been implied that RIPK1 may be involved in tumor necroptosis, the role of RIPK1 in tumor necroptosis has not been evaluated directly and the regulation of tumor necroptosis is largely unknown." (PMID 33976222, 2021). "It therefore appears that increased expression of RIPK1, RIPK3 and MLKL may promote tumour growth." (PMID 34099897, 2021). "Particularly, the role of RIPK1 in tumor necroptosis has not been directly evaluated." (PMID 33976222, 2021). "However, a recent study showed that RIPK1 is needed for inflammatory diseases, but not tumor growth or metastasis." (PMID 33976222, 2021). "Moreover, RIPK1/RIPK3 promote vascular permeability to mediate tumor cells extravasation independent of necroptosis since they allow heat shock protein 27 phosphorylation in lung endothelial cells upon permeability factor treatment (VEGF-A, VEGF-B, FGF-b)." (PMID 33567618, 2021). "Importantly, ZBP1, not RIPK1, deletion blocks tumor necroptosis during tumor development and inhibits metastasis." (PMID 33976222, 2021). "Similarly, the expression of RIPK1 is suppressed by hypoxia, which may participate as a mechanism of resistance of tumor cells to the action of IFN-γ in the tumor microenvironment." (PMID 33807260, 2021).
tumor (continued). "For instance, while multiple studies have indeed found that, whole tumor-biopsy level, high expression of RIPK3 or even sometimes MLKL may predict prolonged cancer patient survival, yet high expression of RIPK1 or MLKL has also been documented to predict worse prognosis for some cancer patients." (PMID 32752206, 2020). "However, whether RIPK1-dependent and RIPK3-independent necroptosis was induced in AdipoRon-administered MIAPaCa-2 tumours remains unknown." (PMID 30038429, 2018). "Interestingly, although the kinase activity of RIPK1 was required, it appeared the loss of kinase activity from RIPK3 was not required in tumor formation in the lung." (PMID 28151480, 2017). "Interestingly, intratumoral administration of LD4172 improved RIPK1 degradation in the tumors, suggesting that the incomplete degradation of RIPK1 in tumors via i.p. injections may be attributed to poor penetration and/or accumulation of LD4172 in tumor tissues." (PMID 39681571, 2024). "Furthermore, in some cases, RIPK1 is not essential for tumor development." (PMID 35725836, 2022). "As we observed that during clonogenic and soft agar growth experiments, RIPK3-, RIPK1-, or MLKL- knockout cells tend to have significantly smaller colonies, we hypothesized that the necroptotic genes may regulate important cytokines required for tumor cell growth." (PMID 26959742, 2016). "In vivo, implantation of RIPK1−/− or MLKL−/− U251 cells into nude mice failed to form subcutaneous tumors, in sharp contrast to robust tumor growth observed for the corresponding wild-type controls." (PMID 41429922, 2025). "MAP3K14 (NIK1), BIRC2 (cIAP1), RIPK1, CASP7, CASP8, and TNF play an important role in inhibiting proliferation and invasion of tumor cells via the activation of the non-canonical NF-κB signaling pathway." (PMID 34638912, 2021). "Nevertheless, our work reveals ZBP1, not RIPK1, as the key mediator upstream of RIPK3 in tumor necroptosis and provide new insights about the regulation of tumor necroptosis during tumor development." (PMID 33976222, 2021). "Consistent with our findings with tumor lysates, the levels of ZBP1 and RIPK3, but not RIPK1, are dramatically increased in GFP-MVT-1 cells isolated from tumors compared to that in cultured cells." (PMID 33976222, 2021). "RIPK1 deletion does not affect the in vitro and in vivo proliferation of MVT-1 cells and MVT-1 tumor growth." (PMID 33976222, 2021). "The mRNA expression levels of RIPK1 and RIPK3 were significantly lower in patients with tumor necrosis (P = 0.04 and P = 2 × 10-5, respectively) than in those without tumor necrosis." (PMID 32742497, 2020). "Similarly, in breast cancer models, the absence of RIPK1, RIPK3, and MLKL results in slower tumor growth and heightened sensitivity to radiotherapy." (PMID 39949740, 2025). "Unlike mice with complete RIPK1 deletion, T cells in Ripk1K45A/K45A mice lack RIPK1 kinase activity but retain their scaffold function, potentially leading to more stable peripheral T cells and enhancing the likelihood of ICD in tumour cells." (PMID 41334873, 2025). "However, the DNA methylation inhibitor 5-Aza-2′-deoxycytidine (5AzadC) and histone deacetylase inhibitor trichostatin A (TSA) did not restore RIPK1 and RIPK3 expression in multiple tumor cell lines." (PMID 25675296, 2015).